TNF (tumor necrosis factor)
Diseases named in the same sentence as TNF in open-access papers (continued):
Sharing a sentence is not in itself a finding about the gene and the disease.
tumor (continued). "It seems that the local intra-tumor IFNγ production by tumor-infiltrated NK, CD4 Th1, and CD8 cytotoxic T lymphocytes together with TNFα supported the generation of high levels of specific antitumor CTLs leading to tumor growth suppression." (PMID 35736195, 2022). "Tumor-bearing mice treated with combination therapy showed higher amounts of CD8+ TILs that expressed IFN-γ, Granzyme B, Perforin, TNF-α, TRAIL and FasL than untreated mice, OX or TIGIT mAb alone." (PMID 36389751, 2022). "Tumor-infiltrating cells (TICs) were isolated from the surgically resected tumors and their capacity to produce IFN-γ, TNF-α and IL-2 was examined by FCM." (PMID 35595859, 2022). "The carrier-free UA NPs exhibited the improved immunostimulatory activity of TNF-α, IL-6, and IFN-β in vitro and inhibited tumor growth with significant activation of CD4+ T cells in vivo, revealing their great potential for cancer immunotherapy." (PMID 36015215, 2022). "The concomitant decrease of TNF-α, COX-2, and Bcl-xL was observed in the treated tumours compared to those of control." (PMID 35386216, 2022). "TNFSF12, also known as TWEAK or CD255, belongs to the tumor necrosis factor (TNF) superfamily, which is expressed in various types of cancer and has been reported to stimulate tumor growth and angiogenesis." (PMID 35602610, 2022). "Here, we showed that CBX7 blocked tumor proliferation through inactivation of the TNF pathway and regulated sensitivity to TKIs via the TNFα/IL6 axis." (PMID 35342353, 2022). "By deleting the TNF receptor, TNFR1, from MC38-OVA tumors, we demonstrate that this hyper-secretion of TNF compensates for reduced synapse-mediated cytotoxic activity against MC38-OVA tumors in vivo, via increased TNF-mediated tumor cell death." (PMID 35874669, 2022). "Since NF-κB activation induces TNF-α secretion, we measured TNF-α levels from plasma and tumor tissues." (PMID 35440077, 2022). "Consequently, TNF-related signaling may exert both tumor promotion and suppression." (PMID 35741080, 2022). "A variety of cytokines derived from tumor cells, including TGF-β, EGF, HGF and TNF-α, mediate the expression of many MPs." (PMID 36591235, 2022). "Binding of TIGIT to CD155 (poliovirus receptor PVR) expressed on tumor cells results in the decreased secretion of pro-inflammatory cytokines such as IFN-γ, IL-17a, and TNF-α, and an increased secretion of the anti-inflammatory cytokine IL-10." (PMID 35345849, 2022). "We evaluated the ex vivo number of IL-2-, IL-6-, IL-10-, IL-12-, TNF-α- and IFN-γ-producing spleen cells, since tumor growth can be affected by cytokines." (PMID 35265317, 2022). "Several studies have shown that the inhibition of apoptosis induced by tumor necrosis factor-α (TNF-α) and the upregulation of hPEBP4 plays a vital role in tumor progression in various types of cancer." (PMID 35682714, 2022). "(A) Tumor size (in mm2) following treatments with anti-CD40, TNFα(i.e. (DC) adjuvant) and tumor-binding antibodies (n=5)." (PMID 36124553, 2022). "The TNF-α and TNF-α receptor (TNFR) complex induces a range of inflammatory genes by activating the nuclear factor-κB (NF-κB) pathway in inflammation-induced tumor growth and metastasis." (PMID 36012284, 2022). "In contrast, the combination of both antibodies significantly inhibited tumor growth, increased the number of tumor-infiltrating CD8+ T cells, and enhanced IFN-γ and TNF-α production of these T cells." (PMID 35132961, 2022). "For instance, elevated tumor necrosis factor alpha (TNF-α) and interleukin-6 (IL-6) secretion is known to promote the metastasis and malignancy of tumor cells." (PMID 36555124, 2022). "Immune cells recognize tumor cell surface antigens and then initiate cellular immunity and kill tumor cells by secreting anti-tumor-related cytokines (INF-γ, TNF-α, and IL-6, etc.)and cell phagocytosis." (PMID 35386701, 2022). "Macrophage secretion of TNF-α induces MIF and EMMPRIN into tumor cells in an NF-κB- and JNK-dependent manner." (PMID 36532066, 2022).
tumor (continued). "We found that TNF-α, IFN-γ, and IL-2, which play vital roles in immunity against tumor growth, were relatively upregulated with these treatments (p< 0.05)." (PMID 35992834, 2022). "For CRC, we reported that pro-inflammatory TNF-α and IFN-γ promote tumor growth and metastasis via induction of MACC1." (PMID 35406521, 2022). "The activated macrophages produce several inflammatory mediators, such as interleukin-6 (IL-6), interleukin-1β (IL-1β), tumor necrosis factor-α (TNF-α) and monocyte chemotactic protein-1 (MCP-1), and disturb the tumor microenvironment." (PMID 36064319, 2022). "In lewis tumor-bearing mice, compared with the CON group, the concentrations of IL-2, TNF-α and INF-γ in the MOD group were decreased (P< 0.001)." (PMID 36389762, 2022). "CD8+ T cells inhibit tumor proliferation by direct lysis of tumor cells or release of IFN-γ and TNF-α." (PMID 36209263, 2022). "The blockade of TGF-β signaling facilitates the infiltration of CTLs in the tumor, but the persistent suppression of TGF-β signaling mediates PD-L1 expression in the tumor via increased secretion of IFN-γ and TNF-α from TILs." (PMID 36358638, 2022). "After treatment with aPNs, not only the number of neutrophils, CD8+, CD4+ T cells, and B cells increased, but also IL-12, TNF-α, and IFN-γ levels elevated significantly in tumor tissues." (PMID 36034656, 2022). "The tumor concentrations of periostin were correlated with tumor levels of VEGF-A, IFN-γ, IL-1β and TNFα." (PMID 35056404, 2022). "Tumor-infiltrating CD8+ T cells from aPD-1 single-treated mice showed an increase of IFNγ, TNFα, and Granzyme B expression compared to untreated controls." (PMID 34423375, 2022). "The releasing of immune-suppressive cytokines suppresses anti-tumor immune responses, including TGF-β, tumor necrosis factor (TNF-α), and IL-6." (PMID 35884355, 2022). "Still adjacent to MAPK signaling is the activity of the tumor necrosis factor (TNF) family and their ambiguous role in tumor development." (PMID 35628297, 2022). "Since the results of our single-nucleus data analysis indicated abundant TNF-α/NFκB and TGF-β signaling in the MLC population and expression of these two cytokines in tumor-infiltrating microglia, we focused our analysis on the effect of these cytokines." (PMID 35803925, 2022). "Host and tumor-derived factors, including proteolysis inducing factor (PIF) and TNF-α, activate NF-κB signaling, enhancing proteolysis and protein degradation." (PMID 35204066, 2022). "Neospora caninum treatment significantly increased the mRNA expression levels of IL-12, IFN-γ, IL-2, IL-10, TNF-α, and PD-L1 in the TME, and IL-12 and IFN-γ in the spleen of tumor-bearing mice (P < 0.05)." (PMID 36138417, 2022). "Mediators released by mast cells (histamine, TNF, VEGF, and tryptase) can increase vascular permeability, enhancing the extravasation and metastatic spread by tumor cells." (PMID 36294305, 2022). "Meanwhile, the inflammatory cytokines (TNF-α, IFN-γ, and IL-6) in heart, liver, lung, or kidney exhibited significant increase after aPD-L1 treatment in 4T1 tumor-bearing mice relative to that of the saline or HPNP treatments." (PMID 35710545, 2022). "Cytokines such as IL-8, TNF-α, CCL20, MIP-2 and MIP-1β have been shown to be dramatically induced by activation of TRAIL-R1 and R2 in different tumor cell lines in an NF-kB dependent manner." (PMID 36496977, 2022). "Based on the AUCell score threshold, the high EMT, TNFα, and Hedgehog cells were mostly concentrated in C7, C14, and C25, but high Notch and BMP cells were discretely distributed among tumor clusters." (PMID 35664733, 2022). "Targeting TAMs to produce pro-inflammatory cytokines, such as IFN-γ and TNF-α, can promote an immune-favorable microenvironment while also producing T cell-specific chemokines, such as CXCL9, to recruit T cells to the tumor." (PMID 35513776, 2022).
tumor (continued). "The effectiveness of the anti‐tumour activity of TNFα can depend on the levels of TNFα released in the ECM and thus on the tumour levels of TACE expression." (PMID 35758207, 2022). "Anti-tumor N1 TANs possess high levels of TNFα, CCL3, ICAM-1, and are also involved in the production of ROS which is cytotoxic to tumor cells." (PMID 36253762, 2022). "In the tumour microenvironment, CD8+ T cells are the predominant forces that exert antitumor effects and release TNF, perforin and granzyme to kill cancer cells after activation." (PMID 36224624, 2022). "On the 14th day after PDT treatment, various immune signal molecules were detected in tumor and lymphoid tissues, including IFN-γ, TNF-α, and CD4+T cells, CD8+ T cells, and DCs." (PMID 35832074, 2022). "This robust anti-tumor effect correlated with the increase in intratumoral CD40+ DCs and the frequency of granzyme B+/IFN-γ+/TNF-α+ polyfunctional OVA peptide-specific CD8+ T cells." (PMID 36311701, 2022). "LKLF (or KLF2) is a zinc finger-containing transcription factor that plays a negative regulatory role in cytotoxic T-lymphocyte (CTL), killing tumor cells by blocking the mimicry of IL2, tumor necrosis factor (TNF)-α, and interferon (IFN)-γ." (PMID 36341370, 2022). "Estimation of common cytokines like IL-6, TNF-α, and IL-1β in brain samples showed a rise in cytokine levels in CMF treated tumor-bearing animals." (PMID 35197512, 2022). "Some reports suggest that in the presence of EGFR ligand secreted by tumor cells, CD3+CD8+CD69+Ki67+ T-lymphocytes produce more IFN-γ and TNF-α and show a stronger antitumor response." (PMID 36142766, 2022). "It has also been reported that neutrophils interact with tumor cells by using the same molecular machinery that induces EMT such as TGF-β, IL-8, CCl2, TNF-α, and IL-17a." (PMID 36091114, 2022). "AAV-Bevacizumab treated mice displayed the highest number of TNF-α+IFN-γ+ tumor specific T cells in the blood, and increases in tumor infiltrating CD8+ T cells and B cells." (PMID 35203573, 2022). "For the first time, the correlation of the salivary levels of TNF-α, IL-1β, and IL-6 with HER2 status, MCP-1, IL-1β, IL-2, and IL-4 with the hormonal status of the tumor was shown." (PMID 36286034, 2022). "An important aspect is tumor necrosis factor-α (TNF-α), which influences tumorigenesis and tumor progression." (PMID 35740575, 2022). "Further, tumor necrosis factor-α (TNF-α), a pro-inflammatory cytokine secreted by TAMs in the TME, has been found to support tumor invasion." (PMID 35327584, 2022). "IL-6 and TNFα pathways suggest a strict connection between inflammation mediators, which may stimulate pre-malignant cell proliferation, angiogenesis, and metastasis, and, tumor cells, which reversely stimulate other cells to produce pro-inflammatory and pro-angiogenic factors." (PMID 35335997, 2022). "In pre-clinical models of breast cancer, tumour irradiation led to enhanced T cell-mediated cytotoxicity, increased levels of T cell-derived IFN-γ and TNF-α, and reduced infiltration of Tregs and MDCSs." (PMID 36139665, 2022). "In turn, activated adipocytes secrete chemokines (CCL2, and CCL5), cytokines (IL-1β, IL-6, TNF-α), and angiogenic factors (VEGF), all required for the promotion of tumor growth, angiogenesis and metastasis." (PMID 35493456, 2022). "TNFα-CSG treatment induces immune-mediated ECM depletion, which alleviates the compression on the tumor blood vessels and enhances tumor perfusion." (PMID 35273916, 2022). "The differential analysis in normal breast tissue and tumor tissue revealed that, except for RIPK1, RIPK3, TNF, MAP3K7, and STAT3, all the other genes showed significantly differential expression in BRCA." (PMID 35686108, 2022). "In conclusion, the depletion of TNF from the colon of CAC-developing mice started a cascade of events, which induced the onset of tumor lesions in the distal colon at intermediate time points; these lesions are characterized by a more aggressive phenotype." (PMID 36499472, 2022).
tumor (continued). "When the Myc-CaP allografts became palpable, tumor volume was measured, PAI was performed, and then host mice were treated with TNF." (PMID 36551505, 2022). "NDV-infected tumor cells stimulated NK cells to produce increased amounts of the effector lymphokines IFN-γ and TNF-α." (PMID 36361831, 2022). "This review is primarily focused on the development and use of a derivative of tumor necrosis factor-α (TNF) that can target and alter the blood–brain-tumor-barrier." (PMID 35890309, 2022). "Tumor necrosis factor-α (TNF-α), the primary factor that induces endothelial barrier dysfunction, was added to the system to simulate the impaired tumor vasculature related to the EPR effect." (PMID 35858898, 2022). "The spleen index and serum levels of TNF-α, IFN-γ, and IL-2 in B16F10 tumor metastasis mice treated with Nr-CWS were significantly increased." (PMID 36110249, 2022). "For the first time, the correlation of salivary levels of TNF-α, IL-1β, and IL-6 with HER2 status, MCP-1, IL-1β, IL-2, and IL-4 with the hormonal status of the tumor was shown." (PMID 36286034, 2022). "By increasing the levels of several factors (e.g., HIF-1α, HGF, EGF, TGF-β, TNF-α, TPA, MMP-3, and even micro-RNA), ROS can enhance and help the EMT and promote the metastasis of tumor cells." (PMID 35659296, 2022). "Macrophages express IL-6, TNF-alpha, and cathepsin B to activate STAT3 pathways in tumor cells, which increases the proliferation and survival of cancer cells treated with various chemotherapeutics." (PMID 35183252, 2022). "Following this, the expression of TNF-α, IFN-γ, perforin, and granzyme B in the peripheral blood of tumor-bearing C3H mice was detected by ELISA." (PMID 35115487, 2022). "Compared with chemotherapy alone, traditional Chinese medicine significantly reduced the serum tumor markers CA125, CEA, and TNF-α levels, immune index CD8+ levels, and adverse reactions." (PMID 35035510, 2022). "Orthotopic transplantation of TNFα-treated BCSC2 showed increased tumor growth, while BCSC1 had homogenous tumor growth when compared to the untreated group." (PMID 36290384, 2022). "NK cells can directly kill tumor cells by cytotoxicity and can also exert immune functions indirectly by secretion of cytokines such as IFN-γ, TNF-α, CCL3, and CCL4." (PMID 35707003, 2022). "In contrast, cholinergic signaling suppresses the CD11b+ myeloid cell population and TNFα expression in the PDAC microenvironment, indicating the tumor suppressive and anti-inflammatory effect of cholinergic signaling." (PMID 36077804, 2022). "In mice, the inclusion of the tumour-draining LNs within the irradiation field led to a significant increase in the amount of tumour infiltrating CD8+ T cells that expressed IFN-γ and TNF-α compared to tumour-targeting RT." (PMID 36139665, 2022). "Another study in PyMT implied that CDDO-Me decreased IL-10 and VEGF levels while increased TNF expression, concomitantly suppressed TAM tumor infiltration, and CD4 Foxp3 regulatory T cells." (PMID 35784750, 2022). "To examine the role of TNF-α and IFN-γ in TSLP-induced PyMt tumor suppression in vivo, we implanted PyMt cells in Tslptg mice and blocked TNF-α and IFN-γ using blocking antibodies." (PMID 36467403, 2022). "Knockdown of tumor cell HMGB1 by shRNA did not inhibit tumor cell growth, whereas CD8+ T cell sensitized by tumor-specific IFN-g and TNF-a can be activated with attenuated functional Tregs." (PMID 36003395, 2022). "The data on anti-RANKL/anti-PD1/anti-CTLA4 combination therapy showed promising results in a higher proportion of tumor-infiltrating CD4+ and CD8+ T cells that can produce both IFNγ and TNFα after anti-RANKL treatment." (PMID 35386705, 2022). "These secreted chemokines, in turn, promote the recruitment of mast cells in the tumor microenvironment and the expression of mast cell angiogenic factors such as VEGF, TNFα, IL-6, IL-8 and FGF-2, which induce the tumor angiogenesis." (PMID 35805075, 2022).
tumor (continued). "Several tumor-derived cytokines such as TGF-β, TNF, IL-6 or IL-10 are able to prevent the maturation of DCs, the infiltration of mature DCs, the presentation of antigens and the activation of T and NK cells." (PMID 36611932, 2022). "In view that downregulation of cellular endogenous c-FLIP protein levels sensitized tumor cells to death receptor-mediated apoptosis, we determined c-FLIP protein levels in Huh7 cells untreated or treated with TNF-α and/or TPL." (PMID 36308574, 2022). "Plasmacytoid DC usually promote the anti-tumor responses via the Toll-like receptor 9 (TLR9) -dependent synthesis of interferon-α (IFN-α), interleukin-6 (IL-6) and tumor necrosis factor-α (TNF-α)." (PMID 36143308, 2022). "For all these reasons by blocking TNFα both studies showed an increase in CD8+ T cell numbers and viability in the tumor microenvironment and draining lymph nodes." (PMID 35847803, 2022). "The PPI network showed that CASP3, JUN, TNF, MMPs, and MAPK are the core hubs of XFZYD in tumour treatment." (PMID 35903326, 2022). "ELISA was used to investigate the effects of EPA on serum cytokine production, including TNF-α, IFN-γ, IL-2, AST, BUN, and IL-6, in H22 tumor-bearing mice." (PMID 35597811, 2022). "The tumor necrosis factor (TNF)-related apoptosis-inducing ligand (TRAIL) is primarily expressed on the surface of immune cells including NK cells, T cells, NK tumor (NKT) cells, DCs, and macrophages." (PMID 36276148, 2022). "Zinc enriches the microbiome in Prevotella, Proteobacteria and Actinobacteria and improves the function of the immune system by increasing the level of pro-inflammatory cytokines such as IL-1β, IL-2, IL-6, TNF-α and IFN-γ in the tumor environment." (PMID 36428677, 2022). "The binding of TNF to TNFR1 triggers a series of intracellular events that ultimately result in the activation of NF-κB and MAPK,23,24 which promotes tumor formation in some types of cancers." (PMID 34995801, 2022). "With this cell model, others have shown that tumor necrosis factor-alpha (TNF-α) gene knockout can markedly reduce the proliferation and clonogenic potential of K562 cells in vitro, and the edited cells displayed impaired tumor xenograft growth in mice models." (PMID 36139356, 2022). "In contrast, NK cells and T cells produce cytokines including TNF-α and IFN-γ; thus, the accumulation of these immune cells in the tumor microenvironment further contributed to the increased levels of cytokines following the CpG-2722 stimulation." (PMID 34581869, 2022). "Activated immune cells, NK cells, in the presence of chemokines such as IL-12, IL-2 and IFN-α/β, metastasize to the tumor area and release IFN-γ, TNF-α and CD107 to exert anti-tumor effects." (PMID 36176401, 2022). "A mechanism of tumor cell death is proposed based on our findings where oxidative stress is induced by NCX4040 from simultaneous induction of NOX4, TNF-α and CHAC1 in tumor cell death." (PMID 36612280, 2022). "The authors also probed mast cells in the TME, as TNF+ and pro-angiogenic VEGFA+ mast cells have been thought to play dueling roles in the tumor." (PMID 35572582, 2022). "As an immunosuppressive microenvironment is favorable for tumor growth and progression, we measured the levels of proinflammatory cytokines (IFN-γ, TNF-α, GM-CSF, and IL-2) and anti-inflammatory cytokines (TGF-β, IL-17, IL-10, and IL-4) within tumors." (PMID 36429032, 2022). "Taken together with in vitro experiments, M1-Exos can promote the macrophage release of tumor necrosis factor TNF-α, which binds to the corresponding receptors of tumor cells to activate the downstream Caspase-3." (PMID 35929830, 2022). "This analysis found the expression of several potent NFκB activating cytokines in microglia, including interleukin-1β (IL-1β), TNF-α, and TNFSF8, with the corresponding receptors being expressed in tumor cells." (PMID 35803925, 2022).